GYS1 (glycogen synthase 1)
Description:
Glycogen synthase participates in the glycogen biosynthetic process along with glycogenin and glycogen branching enzyme. Extends the primer composed of a few glucose units formed by glycogenin by adding new glucose units to it. In this context, glycogen synthase transfers the glycosyl residue from UDP-Glc to the non-reducing end of alpha-1,4-glucan.
Synonyms: GYS; GSY
Tractability: Small molecule: a structure with a bound ligand is known; a high-quality ligand is known. PROTAC: ubiquitination databases record sites on it; its protein half-life has been measured; a small molecule that binds it is known.
Target class: Enzyme; Transferase
Gene: Protein-coding gene on chromosome 19 (48,968,125 to 48,993,337, reverse strand). Ensembl gene ENSG00000104812.
Subcellular location (Human Protein Atlas): Cytosol; Microtubules
Pathways (Reactome):
Disease: Glycogen storage disease type 0 (muscle GYS1); Glycogen storage disease type XV (GYG1); Myoclonic epilepsy of Lafora
Metabolism: Glycogen synthesis
Gene Ontology:
Molecular function: alpha-1,4-glucan glucosyltransferase (UDP-glucose donor) activity; glycogen synthase activity, transferring glucose-1-phosphate; protein binding; D-glucose binding
Biological process: glycogen biosynthetic process; glycogen metabolic process
Cellular component: catalytic complex; membrane; cytoplasm; cytosol; inclusion body
Genetic constraint (gnomAD): Loss-of-function variants: 53 observed, 74.16 expected, observed/expected ratio (o/e) 0.71, 90% interval 0.57 to 0.9. The upper end of that interval is the gene's LOEUF score, 0.9, which puts it in group 3 of 6, group 1 being the genes least tolerant of losing a copy. Missense variants: 823 observed, 928.54 expected, observed/expected ratio (o/e) 0.89, 90% interval 0.84 to 0.94. Synonymous variants: 347 observed, 374.86 expected, observed/expected ratio (o/e) 0.93, 90% interval 0.85 to 1.01.
Gene-disease validity (ClinGen):
ClinGen rates the evidence that GYS1 causes each of these diseases.
glycogen storage disease due to muscle and heart glycogen synthase deficiency (autosomal recessive): Definitive. A glycogen storage disease characterized by muscle and heart glycogen deficiency.
Homologues: Orthologues: chimpanzee GYS1 (100% identical), macaque GYS1 (99% identical), pig GYS1 (98% identical), dog GYS1 (98% identical), guinea pig GYS1 (97% identical), mouse Gys1 (97% identical), rat Gys1 (97% identical), rabbit GYS1 (96% identical), tropical clawed frog gys1 (79% identical), zebrafish gys1 (77% identical), Drosophila melanogaster Glys (54% identical), Caenorhabditis elegans gsy-1 (49% identical). Paralogues in human: GYS2 (67% identical).
Diseases named in the same sentence as GYS1 in open-access papers:
GYS1 is named in the same sentence as 73 diseases in open-access papers, as found by Europe PMC text mining. Sharing a sentence is not in itself a finding about the gene and the disease. The quoted sentences say what the papers report.
breast carcinoma (8 papers, 2016 to 2024). "Among TNBC patients, higher GYS1 expression levels were associated with shorter OS, breast cancer‐specific survival, recurrence‐free survival, and DFS." (PMID 38420162, 2024). "We used well-characterized cohorts of patients with breast cancer to study glycogen and GYS1 mRNA and protein levels." (PMID 37280675, 2023). "We studied the expression of glycogen synthase 1 (GYS1), the key regulator of glycogenesis, and other glycogen-related enzymes in primary tumors of patients with breast cancer and evaluated the impact of GYS1 downregulation in preclinical models." (PMID 37280675, 2023). "Knockdown of GYS1 impairs breast cancer cell proliferation and sensitizes to targeting of mitochondrial protein homeostasis." (PMID 37280675, 2023). "Knockdown of GYS1 made breast cancer cells more vulnerable to inhibition of mitochondrial proteostasis." (PMID 37280675, 2023). "Here, we showed that expression of GYS1 protein and glycogen levels were indeed induced by hypoxia in all the breast cancer cell lines." (PMID 37280675, 2023). "Knockdown of GYS1 impaired proliferation of breast cancer cells, depleted glycogen stores and delayed growth of MDA-MB-231 xenografts." (PMID 37280675, 2023). "We subsequently investigated the impact of GYS1 knockdown on proliferation, glycogen content and sensitivity to mitochondrial targeting in a panel of breast cancer cell lines and in a xenograft model, focusing on TNBC." (PMID 37280675, 2023). "Next, we studied GYS1 expression and impact of GYS1 downregulation in a panel of breast cancer cell lines." (PMID 37280675, 2023). "Our findings highlight GYS1 as potential therapeutic target in breast cancer, especially in TNBC and other highly proliferative subsets." (PMID 37280675, 2023). "Immunohistochemical staining of GYS1 and glycogen was performed on a tissue microarray of primary breast cancers (n = 337)." (PMID 37280675, 2023). "Our findings on the widespread presence of GYS1 in primary breast tumors and the involvement of GYS1 in proliferation make it of interest to extend development and evaluation of GYS1 inhibitors to breast cancer." (PMID 37280675, 2023). "We studied the role of glycogen synthase (GYS1) in breast cancer cell growth and metabolism, and evaluated its role in sensitivity to mitochondrial inhibitors." (PMID 31591445, 2019). "Using siRNAs targeting GYS1, the impact of acute GYS1 knockdown on proliferation was studied in a broad panel of breast cancer cell lines and in a spheroid model of the triple-negative cell line MDAMB231." (PMID 31591445, 2019). "Previous studies have proposed that glycogen accumulation in breast cancer cells is due to HIF1α mediated increase in GYS1 and/or PPP1R3C expression in hypoxia." (PMID 31536495, 2019). "Moreover, acute GYS1 knockdown reduced cell proliferation of breast cancer cells also in normoxia and with glucose levels in the physiological range." (PMID 37280675, 2023). "In human breast cancers, the expression of the key glycogen synthesis enzyme GYS1, its correlation with tumor glycogen levels and the functional consequences of GYS1 downregulation are unknown." (PMID 37280675, 2023). "High mRNA expression of GYS1, but not of the other glycogen synthesis or degradation enzymes, was associated with worse survival in breast cancer patients, especially in patients with TNBC." (PMID 37280675, 2023). "Therefore, we evaluated GYS1 mRNA levels in publicly available breast cancer data and immunohistochemical expression of GYS1 and glycogen in primary human breast cancers." (PMID 37280675, 2023). "Glycogen granules and GYS1 were detected across all breast cancer subtypes and grades." (PMID 37280675, 2023). "Our findings suggest that miR-564 is a potential tumor suppressor that regulates both PI3K and MAPK signaling by directly targeting a network of genes (AKT2, GNA12, GYS1 and SRF) linked to these pathways, and thus controls breast cancer cells proliferation, EMT, migration and invasion." (PMID 27600857, 2016).
breast carcinoma (continued). "Our present study demonstrates a distinct regulatory role of miR-564 in breast cancer progression by direct targeting of a network of genes, namely AKT2, GNA12, GYS1 and SRF that leads to simultaneous inhibition of PI3K and MAPK pathways." (PMID 27600857, 2016). "In conclusion, combined analyses of AKT2, GNA12, GYS1 and SRF expression mimic the effects of miR-564 on tumor progression and survival of breast cancer patients." (PMID 27600857, 2016). "Taken together, our results show that acute downregulation of GYS1 impairs breast cancer proliferation in vitro in 2D and 3D in both hypoxia and normoxia." (PMID 37280675, 2023).
glioma (8 papers, 2014 to 2025). A benign or malignant brain and spinal cord tumor that arises from glial cells (astrocytes, oligodendrocytes, ependymal cells). "Recently, the disulfidptosis related genes (DRGs) SLC3A2, NDUFA11, OXSM, NUBPL, LRPPRC, RPN1, and GYS1 were found to be significantly associated with glioma cells." (PMID 40109666, 2025). "Glioma tissues with increased GYS1 or RPN1 expression also exhibited elevated CD163 expression, aligning with our pan-cancer analysis findings." (PMID 38022537, 2023). "We found a significant positive correlation between the expression of several DRGs (RPN1, GYS1) and StromalScore, ImmuneScore, and ESTIMATEScore in glioma." (PMID 38022537, 2023). "In our evaluation of the risk factors of eight genes, we identified SLC3A2, RPN1, NDUFA11, GYS1 and OXSM as potential risk factors for glioma prognosis." (PMID 38022537, 2023). "We explored their expression in dataset from TCGA and found that LRPPRC was downregulated, while RPN1 and GYS1 were upregulated in TCGA glioma dataset." (PMID 37864127, 2023). "Additionally, a study revealed that high expression of LRPPRC was positively correlated with a favorable prognosis for gliomas, but increased expression of RPN1 and GYS1 was associated with an unfavorable prognosis." (PMID 40109666, 2025). "Additionally, a significant correlation was noted between the mesenchymal scores of low-grade gliomas in the brain and the expression of GYS1 and RPN1." (PMID 40295497, 2025). "The TCGA glioma dataset was used to construct the risk model, and the risk score was calculated using the following formula: risk score = (− 0.3358 × LRPPRC expression) + (1.4536 × RPN1 expression) + (0.5002 × GYS1 expression)." (PMID 37864127, 2023). "The forest map shows that these five genes (SLC3A2, RPN1, NDUFA11, GYS1, OXSM) might be high-risk factors for glioma prognosis." (PMID 38022537, 2023). "TAMs express PYGL and GYS1 highly, which may be one reason for glioma proliferation and immune escape." (PMID 34177761, 2021). "GYS1, NDUFA11, OXSM, RPN1, and SLC3A2 play a role in promoting cancer in glioma, while LRPPRC, NCKAP1, NDUFS1, NUBPL and SLC7A11 play a role in inhibiting tumour." (PMID 39993959, 2025). "In glioma, RPN1, NDUFA11, and GYS1 were significantly positively correlated with StromalScore, ImmuneScore, and ESTIMATEScore." (PMID 38022537, 2023). "We also examined RPN1, GYS1, and CD163 (M2 macrophage marker) expression levels in 83 glioma tissues." (PMID 38022537, 2023). "RPN1 and GYS1 were upregulated in glioma and were negatively correlated with favorable outcome, while LRPPRC1 was downregulated in glioma and positively correlated with favorable outcome." (PMID 37864127, 2023). "Concordantly, it is not clear that the pathophysiological mechanism of GYS1 in regulating gliomas." (PMID 34177761, 2021).
clear cell renal carcinoma (6 papers, 2020 to 2024). A malignant epithelial neoplasm of the kidney characterized by the presence of lipid-containing clear cells within a vascular network. "Research has revealed that GYS1 activates the NF-κB pathway, leading to glycogen buildup and fueling the advancement of clear cell renal cancer." (PMID 39308675, 2024). "In clear cell renal cell carcinomas, glycogen synthase 1 (GYS1) was found to be overexpressed and promoted tumor growth." (PMID 37047105, 2023). "Interestingly, a previous study found that the intermediate product of RPS27A and the interaction between GYS1 and NF-κB promoted the phosphorylation and nuclear translocation of p65 in renal clear cell carcinoma." (PMID 39039432, 2024). "Interestingly, previous studies have found that RPS27A mediates the interaction between GYS1 and NF-κB, promoting the phosphorylation and nuclear entry of p65 in clear cell renal cell carcinoma." (PMID 39039432, 2024). "It was revealed that RPS27A could intermediate the interaction between GYS1 and NF-κB in clear cell renal carcinoma." (PMID 39039432, 2024).
diabetes (6 papers, 2006 to 2024). "In the two diabetes model mice, Gys1 in the muscle of the mice in the combination group was significantly enhanced, indicating that the combination of 2-O-M and insulin can significantly enhance the glycogen synthesis of the muscle in both models." (PMID 35502441, 2022). "Ontological classification demonstrates that these 14 genes are associated with diabetes (ALMS1P; RAET1L; GYS1; RBM47; EFR3B), cancer (RPL27A; SPAM1; PTCH1; ZNF277; USP35; CDC86), or metabolism (C3orf15; AOC2; GOT1)." (PMID 24885560, 2014). "Additionally, GYS1 and PPP1CC have been reported to improve insulin resistance by regulating miR-140-5p in diabetes.Proteasome alpha subunits (PSMAs) have been implicated in the malignant progression of various human cancers." (PMID 38166541, 2024). "We identified key genes (GYS1, PYGL, and PSAT1) from both pathways that have previously been demonstrated to play a role in glucose tolerance/ insulin sensitivity in models of obesity and diabetes and epidemiological studies." (PMID 30483256, 2018). "Polymorphisms in glycogen synthase kinase beta (GSK3B), a regulator of glycogen synthase activity, and skeletal muscle glycogen synthase 1 (GYS1) have been examined in several studies, but have generally failed to associate with diabetes or measures of insulin resistance." (PMID 16700901, 2006).
Insulin resistance (6 papers, 2006 to 2024). Increased resistance towards insulin, that is, diminished effectiveness of insulin in reducing blood glucose levels. "A common variant in the GYS1 gene has been associated with type 2 diabetes and insulin resistance, as well as increased risk of cardiovascular morbidity and mortality." (PMID 18232730, 2008). "In addition, for circFAT3 KD, genes related to insulin signaling and insulin resistance (PPARGC1A, SLC27A2, PPARGC1B, PRKCQ, GYS1, and IRS1) were the top hits." (PMID 36840844, 2023). "Second, impaired glycogen synthesis in muscle does not a priori lead to insulin resistance, impaired glucose tolerance, or diabetes, since glucose tolerance was normal in carriers of mutations in both the PPP1R3A and GYS1 genes." (PMID 18232730, 2008).
cardiomyopathy (5 papers, 2008 to 2025). A disease of the heart muscle or myocardium proper. "Given that mutations in PPP1R3A are seen in one out of 70, and in GYS1 in one out of 100 white people, it will be important to screen for these mutations in individuals with signs of exercise intolerance or cardiomyopathy." (PMID 18232730, 2008). "This was certainly true when this work was performed, but very recently a homozygous mutation was described in the GYS1 gene in children with severe cardiomyopathy and exercise intolerance." (PMID 18232730, 2008). "Inborn homozygous GYS1 deficiency can lead to cardiomyopathy and cardiac arrest in some patients." (PMID 37280675, 2023). "All these evidences suggested that glycogen deposits in PRKAG2 cardiomyopathy was due to enhanced expression of GYS1." (PMID 35360035, 2022). "Humans who have a total absence of GYS1 due to rare inherited mutations (MIM 611556) are healthy except for late-childhood cardiomyopathy, while no health issues were found with 50% residual GYS1 activities." (PMID 33523197, 2019).
glioblastoma (5 papers, 2021 to 2025). The most malignant astrocytic tumor (WHO grade IV). "GYS1 is one of the main regulators of glycogen synthesis, and GYS1 inhibition causes glycogen accumulation in glioblastoma cells, leading to proliferation and migration suppression and formation of ROS, indicating GYS1 inhibition may be a promising therapeutic target for glioma." (PMID 37864127, 2023). "GYS1 inhibition, in primary glioblastoma cells has been shown to induce cellular accumulation of glycogen, which has been associated with a reduction of proliferation and migration, and an increase of cellular differentiation." (PMID 33727611, 2021). "Studies of tumors showed that GYS1—the most important rate-limiting enzyme functioning in the last step of glycogen synthesis, was rapidly induced under hypoxic conditions and positively correlated with glycogen accumulation in glioblastoma." (PMID 34177761, 2021). "However, SB747651A ́s multi-targeting of glioblastoma metabolism, mediated by GSK3 and GYS1, combined with mTOR and CREB inhibition, and a decrease of SOX2 expression, has not previously been described." (PMID 33727611, 2021).
Lafora disease (4 papers, 2022 to 2023). Lafora disease (LD) is a rare, inherited, severe, progressive myoclonic epilepsy characterized by myoclonus and/or generalized seizures, visual hallucinations (partial occipital seizures), and progressive neurological decline. "This work provides proof of concept that a Gys1-ASO halts disease progression of EPM2B mutations of Lafora disease." (PMID 37700152, 2023). "For example, the GYS1 gene may be knocked down to prevent the overproduction of the substrate glycogen, which accumulates to cause Lafora disease." (PMID 35847198, 2022). "ICV injection of an ASO targeting the mRNA of brain-expressed GYS1 in a murine model of Lafora disease led to inhibition of further accumulation of Lafora bodies in older mice that had already formed bodies and prevented Lafora body formation in young mice that had not yet formed any." (PMID 35250833, 2022). "Recently, a proof-of-concept paper demonstrated that a viral vector carrying clustered regularly interspaced short palindromic repeats (CRISPR)/Cas9 with a guide RNA could be used to target and cut the Gys1 gene responsible for producing brain glycogen that leads to Lafora bodies and Lafora disease." (PMID 35847198, 2022). "While mutations in GYS1 are not responsible for Lafora disease, down-regulation of glycogen synthase with an ASO could lead to decreased elongation of glycogen polymers, thereby decreasing the formation of Lafora bodies." (PMID 35250833, 2022).
glycogenosis (3 papers, 2009 to 2022). "Equine type 1 polysaccharide storage myopathy (PSSM1), a common glycogenosis associated with an R309H founder mutation in the glycogen synthase 1 gene (GYS1), shares pathological features with several human myopathies." (PMID 22860112, 2012). "The screened GYS1, PYGL and PHKG1 genes play crucial roles in the glycogenolysis step of the glucagon signaling pathway, and their overexpression destabilizes glycogenolysis and predisposes one to glycogen storage disease, which can lead to cirrhosis and liver fibrosis." (PMID 36430769, 2022). "It has been suggested that another non-GYS1 glycogenosis could explain these 22 PSSM cases." (PMID 19664222, 2009). "Most of the PSSM cases diagnosed by histology were heterozygous for the mutation but 22 PSSM cases were of the homozygous wild type and the GYS1 mutation alone could not explain the glycogenosis." (PMID 19664222, 2009).
Pompe disease (3 papers, 2016 to 2025). "Using both prevention and reversal treatment modalities, we demonstrated the potential of the Gys1 ASO approach to serve as efficacious SRT in the Gaa−/− mouse model of Pompe disease." (PMID 40268518, 2025). "Altogether the preclinical evidence suggests that reducing GYS1 can be a potential therapeutic approach in Pompe disease, either alone, or in combination with ERT." (PMID 40268518, 2025). "It is expected that GYS1 ASOs have the potential to be used as an alternative treatment approach, as monotherapy in LOPD with little or no cardiac involvement, or in combination with ERT primarily for IOPD in future clinical trials for patients with Pompe disease." (PMID 40268518, 2025). "The combination of Gys1 ASO#2 and ERT may work synergistically to improve cellular homeostasis and promote more effective muscle recovery, particularly in tissues affected by glycogen accumulation and autophagic dysfunction, such as skeletal muscle in Pompe disease." (PMID 40268518, 2025).